RNU2-52P (RNA, U2 small nuclear 52, pseudogene)
Gene: Small nuclear RNA gene on chromosome 20 (41,024,205 to 41,024,394, forward strand). Ensembl gene ENSG00000222612.
Homologues: Orthologues: chimpanzee U2 (99% identical), macaque U2 (97% identical), guinea pig U2 (84% identical), pig U2 (84% identical), dog U2 (82% identical), rat LOC120095786 (80% identical), rabbit U2 (46% identical). Paralogues in human: U2 (89% identical), RNU2-2 (87% identical), RNU2-4P (87% identical), U2 (85% identical), RNU2-3P (85% identical), RNU2-48P (83% identical), RNU2-17P (82% identical), RNU2-26P (82% identical), RNU2-5P (82% identical), RNU2-25P (82% identical), RNU2-49P (82% identical), RNU2-57P (82% identical), and 65 more.